PIK3CA (phosphatidylinositol-4,5-bisphosphate 3-kinase catalytic subunit alpha)
Diseases named in the same sentence as PIK3CA in open-access papers (continued):
Sharing a sentence is not in itself a finding about the gene and the disease.
gastric cancer (continued). "Mutations in PIK3CA exons 9 and 20 were observed in 25 of the 208 (12 %) gastric cancer patients." (PMID 27388016, 2016). "Additionally, we reviewed the rate of PIK3CA mutations in gastric cancer and the association between PIK3CA mutations and prognosis in human cancers." (PMID 27388016, 2016). "Whether PIK3CA amplifications are associated with the prognosis of gastric cancer remains controversial." (PMID 26701847, 2016). "Mutations in PIK3CA were identified in 3 of 12 gastric cancers (25%)." (PMID 25003395, 2014). "Mutations in PIK3CA gene occurred in 14.3% of the MSI gastric cancers." (PMID 25003395, 2014). "PIK3CA mutations are rare, but their amplification is very common in gastric carcinoma." (PMID 25003395, 2014). "PIK3CA mutations in exons 9 and 20 were present in 10.6% of gastric carcinomas." (PMID 25003395, 2014). "A total of 8 PIK3CA mutations (7.1%) were found in the 113 gastric cancers." (PMID 22292935, 2012). "Given PIK3CA mutations and amplification play the critical role in gastric tumorigenesis, we investigated their clinical significances and prognostic values in a large cohort of gastric cancer patients who had known survival data." (PMID 22292935, 2012). "Importantly, Kaplan-Meier survival curves revealed that PIK3CA amplification was significantly positively associated with poor survival of gastric cancer patients." (PMID 22292935, 2012). "The most frequent somatic mutation in gastric cancer was PIK3CA mutation which could be a potential therapeutic target in this population." (PMID 22723903, 2012). "Thus, we excluded the patients with residual tumor to explore the association of PIK3CA mutations and amplification with the survival of gastric cancer patients again." (PMID 22292935, 2012). "The overall prevalence of PIK3CA mutations implies an important role for PIK3CA in gastric cancer." (PMID 20398348, 2010). "Our data suggested that activation of the PI3K signalling pathway in gastric cancer may be achieved through up-regulation or mutation of PIK3CA, in which the latter may be a consequence of mismatch repair deficiency." (PMID 15784156, 2005). "In this study, we have reported the presence of PIK3CA gene mutation in 4.3% of gastric cancer." (PMID 15784156, 2005). "Moreover, though the overall incidence of KRAS mutation in the studied population was low (8 in 94), 2 of the 4 gastric cancers with PIK3CA mutation also harboured a KRAS mutation." (PMID 15784156, 2005). "The significance of PIK3CA mutations in gastric cancer remains unclear." (PMID 27388016, 2016). "In a previous high-throughput profiling of gastric cancers using OncoMap v3, percentage of samples with mutation was 38.2%, which is slightly higher than our incidences and the most frequent mutations were PIK3CA mutations (14.5%) followed by KRAS genes (7.7%) and PTEN (2.5%)." (PMID 22723903, 2012). "In gastric cancer, high PIK3CA protein expression correlates with poor prognosis, though gene amplification or mutation showed no significant prognostic link." (PMID 40149275, 2025). "ARID1A is a frequently mutated gene in gastric cancers (GCs), particularly in those associated with the Epstein-Barr virus (EBV), which also often shows PIK3CA mutations and CDKN2A silencing." (PMID 40761291, 2025). "The genes most frequently associated with gastric cancer in Asian populations include FAT4, a tumor suppressor whose mutations promote tumor growth and metastasis, and PIK3CA, an oncogene involved in the PI3K/AKT pathway." (PMID 40149995, 2025). "Amplification of chromosome regions containing the PIK3CA gene has been identified in several human cancers, including ovarian, cervical, head and neck, and gastric cancers." (PMID 40041495, 2025). "The results indicated that LBP exerts its anti-cancer effects by influencing the miR-202-5p/PIK3CA axis in gastric cancer." (PMID 39897859, 2025).
gastric cancer (continued). "Similar results were obtained in EBV-infected SNU-719 gastric carcinoma cells, EBV-uninfected PIK3CA mutant HGC-27 gastric carcinoma, and in PIK3CA wildtype SNU-1 gastric carcinoma cells." (PMID 41315365, 2025). "Gastric cancer peripheral blood has been found to include ctDNA ofthe PIK3CA gene; the detection limit is low, at 1.0 × 10∧–20 mol/L, and there is potential for real-time detectionin patient serum samples." (PMID 38950521, 2024). "Its first-in-human phase Ia trial in pretreated solid tumors with PIK3CA mutations showed its tolerability and efficacy in several types of PIK3CA-mutant solid tumors such as breast, ovarian, and gastric cancers." (PMID 38396649, 2024). "Overexpression of the PIK3CA gene in gastric cancer has been suggested as an indication for targeted therapeutic drugs such as sorafenib." (PMID 38675376, 2024). "Further research is needed to fully understand the role of PIK3CA in gastric cancer and its potential implications for diagnosis and treatment." (PMID 38675376, 2024). "As for other genes of interest in the molecular landscape of gastric cancer, the neoplastic tissues of 3 patients (6%) were characterized by high levels of the PIK3CA mRNA." (PMID 39323992, 2024). "Detection of the PIK3CA gene in gastric cancer peripheralblood; electropolymerized PXA on MoS2 electrode; alteration in self-signalfollowing ssDNA hybridization with target DNA; 1.8 × 10∧–17 mol/L detection limit." (PMID 38950521, 2024). "Previous studies have revealed that abnormally elevated PIK3CA contributes to the growth and invasion of multiple cancers, including ovarian, breast, colorectal, and gastric cancers." (PMID 39097730, 2024). "A range of mutations within the PIK3CA gene and amplification of receptor tyrosine kinase genes such as EGFR and HER2 were detected in the analyzed cases of gastric cancer." (PMID 37894443, 2023). "Epstein–Barr virus‐positive gastric cancer frequently shows mutations in ARID1A and PIK3CA and has a more distinct CpG methylation profile when compared to MSI‐type GC." (PMID 38041544, 2023). "It was noted that several classic gastric cancer driver genes were more frequently mutated in the low-CDK6-AS1 expression group than in the high-expression group, such as ARID1A and PIK3CA." (PMID 35571043, 2022). "Our study also found many patients with clonal pathogenic mutations in the RAS/RAF pathway gene KRAS and the PI3K/MTOR/AKT pathway gene PIK3CA, providing further evidence of their importance in gastric cancer biology." (PMID 36970058, 2022). "Phosphatidylinostitol 3-kinase catalytic subunit (PIK3CA) can decrease the invasive capacity of gastric cancer cells in vitro." (PMID 36292949, 2022). "Further analysis of the TCGA gastric cancer patient data revealed that PI3K/AKT/mTORC1 signaling pathway alterations occur in 33% of gastric cancer (142 of 441 samples) with PIK3CA, AKT, and PTEN alterations being the most common genetic alterations." (PMID 35758651, 2022). "A preliminary evaluation of the anti-tumor efficacy of CYH33 suggested that this PI3Kα inhibitor is effective for treating several types of PIK3CA-mutant solid tumors such as breast, ovarian, and gastric cancers." (PMID 36385120, 2022). "In gastric cancer, high PIK3CA protein expression is closely related to tumor invasiveness, tumor phenotype and poor survival of patients." (PMID 33987081, 2021). "5, 5, 3, and 2 mutations of KRAS, PIK3CA, ERBB2 and CTNNB1 were observed in 4, 4, 3, and 2 gastric cancers, respectively (5, 3, 3, and 2 hotspot mutations, respectively)." (PMID 34873204, 2021).
gastric cancer (continued). "It is reported that PIK3CA is a target of miR-142-5p in non-small cell lung cancer, gastric cancer, and pancreatic cancer." (PMID 33509213, 2021). "In gastric cancer, alpelisib and paclitaxel demonstrated synergistic anti-proliferative and anti-migratory effects in PIK3CA mutant cells." (PMID 33498451, 2021). "For instance, ctDNA analysis has been successfully used to detect resistant mutations in genes such as EGFR, ERBB2, PIK3CA, and RAS, in various cancers including NSCLC, CRC, and gastric cancer." (PMID 33673461, 2021). "Combined with somatic hotspot mutations, ERBB2 was activated in 9 of the 90 gastric cancers (10%), KRAS was in 6 (7%), and PIK3CA was in 4 (4%)." (PMID 34873204, 2021). "A study of gastric cancer patients detected a high frequency of mutations in MLL4, ERBB3, FBXW7, MLL3, mtor(RPTOR), NOTCH1, PIK3CA, KRAS, ERBB4 and EGFR." (PMID 33909629, 2021). "PIK3CA mutations are frequently observed in various human cancers including gastric cancer (GC)." (PMID 32704014, 2020). "Furthermore, it is reported that the overall clinical response rate of gastric cancer patients to PD-1 inhibition was significantly higher in patients with PD-L1+ tumor cells, PIK3CA mutation, MMR deficiency, and EBV+ tumors, suggesting these subsets could be candidates for immunotherapy." (PMID 31941061, 2020). "Former research has revealed that abnormally increased PIK3CA contributes to the growth and invasion of multiple cancer cell line, including breast, ovarian, colorectal, and gastric cancers." (PMID 33344221, 2020). "In esophageal and gastric carcinoma, the presence of node metastases was significantly correlated with positive staining for PIK3CA." (PMID 33287350, 2020). "VGLL1 expression was positively correlated with PIK3CA and PIK3CB, which are associated with poor OS in gastric cancer patients." (PMID 31816819, 2019). "In this study, we discovered VGLL1 as a novel prognostic biomarker correlated with PIK3CA or PIK3CB in gastric cancer." (PMID 31816819, 2019). "Mutations in PIK3CA which encodes p110 catalytic subunit of PI3K have been observed in various human cancers, including gastric cancers." (PMID 30514953, 2018). "The authors identified distinct mutations and epigenetic profiles (recurrent PIK3CA mutations, high DNA hypermethylation levels and amplification of JAK2, CD274 and PDCD1LG2) in EBV-associated gastric cancer cases." (PMID 28454117, 2017). "However, the significance of PIK3CA mutations in gastric cancer remains unclear." (PMID 27388016, 2016). "Patients with PIK3CA amplifications were more likely to have diffuse-type and poorly differentiated gastric cancers and were more likely to experience peritoneal recurrence compared with those without PIK3CA amplifications." (PMID 26701847, 2016). "During the follow-up of gastric cancer patients with PIK3CA amplifications, physicians should be aware of the possibility of peritoneal recurrence." (PMID 26701847, 2016).
gastric cancer (continued). "Among the 11 patients, two patients had simultaneous EBV infection and PIK3CA mutations and both of them had stage III gastric cancer and had tumor recurrence within one year after surgery." (PMID 26701847, 2016). "In support of this, miR-148b was reported to be downregulated in gastric cancers and aggressive breast tumors where it was identified to target multiple genes involved in cell signaling, including PIK3CA." (PMID 25630670, 2015). "Direct sequencing of gastric cancer specimens revealed the proportion of KRAS, BRAF, and PIK3CA mutations." (PMID 26207151, 2015). "Chromosome copy number abnormalities have been frequently identified in gastric cancer, including PIK3CA amplification." (PMID 22292935, 2012). "There is an array of PIK3CA inhibitors and few of these drugs are being tested in early phase trials for gastric cancer." (PMID 22723903, 2012). "As the first step to understand the role of PIK3CA gene in gastric cancer, we sequenced exons 9 and 20 of this gene in a large cohort of gastric cancers." (PMID 22292935, 2012). "Statistical analysis showed that copy number of PIK3CA gene in gastric cancers was significantly higher than normal gastric tissues (P < 0.0001)." (PMID 22292935, 2012). "An association between PIK3CA mutations and MSI has been reported or at least suggested in both colon and stomach cancer." (PMID 20398348, 2010). "We analysed 264 gastric cancers, including 39 with microsatellite instability (MSI), for mutations in the two PIK3CA hotspots in exons 9 and 20 by direct sequencing of DNA obtained from microdissected cancer cells." (PMID 20398348, 2010). "Since over-expression of PIK3CA has been reported in gastric cancer, we have also extracted PIK3CA expression data from our previous cDNA microarray study of these cases." (PMID 15784156, 2005). "PIK3CA, the catalytic subunit of PI3K, coordinates a diverse range of cell functions, including proliferation and survival, and is the third most frequently mutated gene in stomach cancer." (PMID 38674412, 2024). "Interestingly, the interrogation of gastric cancer databases showed that the co-occurrence of KRAS and PIK3CA pathway mutations is around twofold more frequent for A146T than for the other mutants (66% vs 23%, Suppl." (PMID 38261067, 2024). "Interestingly, a prior report suggests that the presence of PIK3CA mutations correlates with better outcome after ICI therapy, at least in gastric cancer patients." (PMID 38632994, 2024). "For example, PIK3CA mutation is associated with EBV-positive gastric adenocarcinoma, and KMT2D may promote the proliferation of gastric cancer cells." (PMID 39555091, 2024). "Furthermore, miR-152-5p has been reported to suppress tumors from gastric cancer by targeting PIK3CA." (PMID 37925170, 2023). "One study found that gastric cancer patients with PIK3CA, LRP1B and AHNAK2 mutations had a better prognosis, and that investigating the molecular mechanisms of the three-gene interaction has potential value in improving the prognosis of gastric cancer." (PMID 38033502, 2023). "SB-PCCs may harbor RHOA mutations, which are reminiscent of the diffuse subtype of gastric cancers or appendiceal GCAs, while KRAS and PIK3CA mutations, commonly involved in colorectal and small bowel adenocarcinomas, are not typical of such cancers." (PMID 36812376, 2023).
gastric cancer (continued). "Patients with EBVaGCs with intestinal or poorly cohesive carcinoma histology frequently harbored driver mutations other than PIK3CA, whereas those with EBVaGCs with gastric carcinoma with lymphoid stroma histology lacked other driver mutations." (PMID 37945587, 2023). "PIK3CA amplification could activate the PI3K/Akt pathway in gastric cancer resulting in the poor survival rates of gastric cancer patients." (PMID 36292949, 2022). "These polymer biosensors were electropolymerized by poly-xanthurenic acid (PXA) on the surface of a MoS2 electrode that was prepared in advance, thus forming an ideal interface for the PIK3CA gene expressed in the peripheral blood of patients with gastric cancer." (PMID 36005048, 2022). "A study constructed a decision tree using mutations in PIK3CA, MEF2C, SLC11A1, and KIF15 to divided patient sub-cohorts with elevated PD-L1 expression, which contribute to identify the novel prognostic biomarkers of Gastric Cancer." (PMID 35359374, 2022). "Meanwhile, a gastric cancer cell line HGC27 which harbors only a PIK3CA mutation and two other gastric cancer cell lines SNU16 and SNU5 lacking PIK3CA and CTNNB1 mutations were used to test the specificity of synergistic effects of copanlisib and mebendazole." (PMID 34493320, 2021). "However, OS analysis indicated theassociation of better prognosis of gastric cancer with highexpression of PIK3CA, suggesting that the role of PIK3CA ingastric cancer is worthy of further exploration." (PMID 33987081, 2021). "Somatic mutations in PIK3CA, which encodes the catalytic subunit of the phosphatidylinositol 3-kinase (PI3K) complex, have been detected in a broad spectrum of tumor types, including gastric cancer." (PMID 32070411, 2020). "In gastric cancer, the expression of AKT in the cytoplasm is significantly increased in patients with phosphatidylinositol-4, 5-bisphosphonate 3-kinase catalytic subunit (PIK3CA) mutation." (PMID 33354218, 2020). "Moreover, in gastric cancer, it has been well known that APOBEC-mutation signature and PIK3CA mutation were frequently observed in EBV+ pts." (PMID 30704511, 2019). "EBVaGC comprises 5%–10% of gastric cancer cases and has several characteristics distinct from EBV-negative gastric cancers, such as massive lymphocytic infiltration, frequent genetic mutations in PIK3CA and ARID1A, and global hypermethylation of CpG islands." (PMID 30695048, 2019). "However, the relationship between PIK3CA expression and gastric cancer (GC) prognosis remains controversial." (PMID 29484141, 2018). "We also found that mRNA expression levels of CDH1, CDKN1A, and EP300 were significantly reduced while those of RhoA, ROCK1, ROCK2, PIK3CA, and CCND1 were significantly increased in gastric cancers with reduced or loss of NKX6.3 expression compared to those in NKX6.3 positive cases." (PMID 30514953, 2018). "In addition, expression levels of CDH1, CDKN1A, and EP300 were reduced while expression levels of RhoA, ROCK1, ROCK2, PIK3CA, and CCND1 were increased in gastric cancer tissues with reduced or loss of NKX6.3 expression." (PMID 30514953, 2018). "Mutations in PIK3CA did not correlate with prognosis in patients with gastric cancer, providing additional evidence for the lack of relationship between the two." (PMID 27388016, 2016). "Moreover, physicians should be alert to peritoneal recurrence during the follow-up period, particularly in gastric cancer patients with PIK3CA amplifications." (PMID 26701847, 2016). "We found that PIK3CA mutations did not correlate with prognosis in patients with gastric cancer, providing additional evidence for the lack of relationship between the two." (PMID 27388016, 2016).